CCR7 (C-C motif chemokine receptor 7)
Diseases named in the same sentence as CCR7 in open-access papers (continued):
Sharing a sentence is not in itself a finding about the gene and the disease.
breast cancer (continued). "In order to confirm the biological functions of CXCL9, CCR7, and SOCS1 in breast cancer, the plasmids for overexpressing CXCL9, CCR7, and SOCS1 were transfected into MCF-7/T cells." (PMID 32974144, 2020). "Moreover, CCR7 expression may enhance breast cancer cells’ migration to lymph nodes." (PMID 32340161, 2020). "The interaction between CCR7 and CCL21 has been shown to improve the immunogenicity of CCR7-expressing breast cancer cells." (PMID 32340161, 2020). "In TGF-β-induced EMT, the expression of C-C motif chemokine receptor 7 (CCR7), the CCL21 receptor, is increased and this facilitates breast cancer cell migration." (PMID 32439908, 2020). "More importantly, the mRNA expressions of CXCL9, CCR7, and SOCS1 in breast cancer cells were observed notably higher in the taxanes-sensitive cell lines (MCF-7 and BCap37) than taxanes-resistant cell lines (MCF-7/T and Bads-200)." (PMID 32974144, 2020). "For CCR7, it was reported that sialylation is important for its functions in promoting CCL19 induced breast cancer cell growth." (PMID 32778659, 2020). "In conclusion, our study shed light on clinical theragnostic relationships between miR-335-5p/CXCL9, let-7c-5p/CCR7/SOCS1 axes, and taxanes-resistance in breast cancer." (PMID 32974144, 2020). "All the outcomes strongly confirmed that CXCL9, CCR7, and SOCS1 screened out via WGCNA participated in the regulation of taxanes-sensitivity in breast cancer cells." (PMID 32974144, 2020). "In total, the results strongly suggested CXCL9, CCR7, and SOCS1 played an important role in chemo-resistance of breast cancer." (PMID 32974144, 2020). "The silencing of CCR7 decreased the in vitro proliferation, migration and invasion of CCL21/CCL19-induced MCF-7 and MDA-MB-231 breast cancer cells." (PMID 32340161, 2020). "For example, breast cancer was found to express the chemokine receptors CXCR4 and CCR7 at high levels." (PMID 31533220, 2019). "Mature DC membrane markers were analyzed by flow cytometry, and Mo-DCs obtained from breast cancer patients showed less HLA-DR, CD11c CD86, CD80, and CCR7 expressions when compared to Mo-DCs from healthy donors." (PMID 31827382, 2019). "Subsequent studies by this laboratory revealed that CCR7 upregulation resulted from AKT-mediated phosphorylation and the activation of the transcription factor Sp1 in breast cancer cells." (PMID 29596308, 2018). "Our data exhibited that knock‐down of CCR7 reduced the EMT, migration, and invasion of breast cancer cells." (PMID 28378417, 2017). "In this research, human breast cancer MCF‐7 and MDA‐MB‐231cells were treated with CCL19 and small‐interfering RNA (CCR7 siRNA) for activation and inhibition of CCR7, respectively." (PMID 28378417, 2017). "The impact of the CCL21/CCR7 axis in the molecular mechanism of the adhesion of NKL3 cells and of MDA-MB-231 breast cancer cells was reduced in a hypoxic tumor environment." (PMID 28416768, 2017). "In breast cancer, chemokine receptors such as CXCR4 and CCR7 play a critical role in determining the metastatic destination of tumor cells." (PMID 29155879, 2017). "These include the signaling gene TGFBR1, the proto-oncogene MYB as well as many immune-related genes such as CCR7 and FCRL3, reinforcing evidence for a role of immune components in influencing breast cancer patients’ prognosis." (PMID 28059167, 2017). "Importantly, these findings may be translatable to human disease, as analysis of a published database available in Oncomine showed that expression of CCR7 and Notch1 are significantly correlated in primary human breast cancers, particularly in higher grade tumors." (PMID 28137279, 2017). "Addtionally, CCL21/CCR7 chemokine axis regulates the expression and secretion of VEGF-C in human breast cancer cells, and contributes to LECs lymphangiogenesis and breast cancer-induced lymphangiogenesis." (PMID 27166194, 2016).
breast cancer (continued). "The expression analysis of CCL21/CCR7 pair and lymphatic endothelial cell (LEC) markers in breast cancer specimens was performed by means of quantitative real-time PCR." (PMID 25744065, 2015). "By utilizing CCR7 and CCL21 gene manipulated breast cancer cell implants into orthotopic sites of nude mice, lymphatic vessel formation was assessed through quantitative real-time PCR, immunohistochemistry and immunofluorescence assays." (PMID 25744065, 2015). "Accumulating evidences suggested that breast cancer cells highly express active CCR7 and CXCR4 which are responsible for directing breast cancer cell migration and invasion, and it potentially leads to metastasis to liver, lung, bone marrow and lymph nodes." (PMID 26592552, 2015). "Our previous study demonstrated that activation of TAK1 increases the expression of chemokine (C-C motif) receptor 7 (CCR7) and promotes lymphatic invasion ability of breast cancer cells." (PMID 25557171, 2015). "We demonstrate here that CCR7 activation by CCL21 binding can induce a significant increase in both AKT and ERK1/2 phosphorylation in breast cancer cells; however, only the former pathway is required for VEGF-C up-regulation and secretion." (PMID 25744065, 2015). "The expression of chemokine receptors is known to be associated with cancer metastases, such as CXCR4, CCR7 and CCR10 in breast cancer and CXCR5, CCR6, CCR7, and CCR4 in pancreatic, gastric and prostate cancers." (PMID 25245466, 2014). "Additional studies show that combined CCR7 and CXCR4 expression is also correlated with lymph nodes metastasis in breast cancer, gastric cancer, cervical cancer, and melanoma." (PMID 24259307, 2013). "Here we investigated M13HS hybrid cell lines, derived from spontaneous fusion events between M13SV1-EGFP-Neo breast epithelial cells exhibiting stem cell characteristics and HS578T-Hyg breast cancer cells, concerning CCL21/CCR7 signaling." (PMID 23667660, 2013). "The CCR7 expression level of HS578T-Hyg breast cancer cells was similar to hybrid cell lines, whereas M13SV1-EGFP-Neo cells exhibited a weaker CCR7 expression." (PMID 23667660, 2013). "Analysis of breast cancer and lymph nodes tissue microarrays of the same patients revealed that CXCR4 and CCR7 together with their ligands as well as EGFR were significantly higher expressed in tumor cells with lymph node metastasis." (PMID 23667660, 2013). "M13HS-2 and M13HS-8 hybrid cell lines, which derived from spontaneous fusion events between M13SV1-EGFP-Neo human breast epithelial cells exhibiting stem cell characteristics and HS578T-Hyg human breast cancer cells, express the CCL21 receptor CCR7." (PMID 23667660, 2013). "First, the expression of mRNA for CCR7 and its ligands CCL19 and CCL21 was confirmed in breast cancer cell lines and in malignant and normal tissues from breast cancer patients." (PMID 22251626, 2012). "The expression of CCR7, its ligand CCL21, and let-7a was detected in breast cancer cell lines and in breast cancer patient tissues." (PMID 22251626, 2012). "In breast cancer cells, signalling through CXCR4 or CCR7 mediates actin polymerization and pseudopodia formation and subsequently induces chemotactic and invasive responses." (PMID 23905066, 2012). "In contrast, silencing (inhibition) of let-7a resulted in increases in CCR7 expression, cell migration, and cell invasion in MCF-7 breast cancer cells, consistent with the results of CCR7 silencing by its specific siRNA." (PMID 22251626, 2012). "Let-7a was also found to target CCR7 3'UTR directly, thereby downregulating breast cancer cell migration and invasion." (PMID 22251626, 2012). "First, a higher expression of both CCR7 and CCL21 in malignant tissues than in their normal counterparts from breast cancer patients was observed." (PMID 22251626, 2012). "Breast cancer cells specifically express functionally active CXCR4 and CCR7, which can trigger actin polymerization, pseudopodia formation and directional movements." (PMID 22253872, 2012).
breast cancer (continued). "This study investigated the expression of CXCR4, CCR7, CXCL12, CCL21, and EGFR to illustrate the role of these biomarkers in breast cancer metastasis and prognosis." (PMID 20181250, 2010). "The CXCR4, CCR7, CXCL12, CCL21, and EGFR biomarkers were analyzed along with ER, PR, and HER-2/neu in breast cancer tissue microarray (TMA) specimens, including 200 primary breast cancer specimens by immunohistochemistry." (PMID 20181250, 2010). "Out of all the known chemokine receptors, breast cancer cells specifically express active CXCR4 and CCR7, the ligands of which are HCXCL12 and CCL21, respectively." (PMID 20181250, 2010). "This study aims to verify the significance of CXCR4, CCR7 and their CXCL12 and CCL21 ligands, together with EGFR in the evaluation of metastasis and the prognosis of breast cancer." (PMID 20181250, 2010). "A landmark study clearly demonstrated that breast cancer cells that expressed the chemokine receptors, CXCR4 and CC chemokine receptor 7 (CCR7), were capable of preferentially homing to particular tissues." (PMID 17687340, 2007). "Analysis of CCR7 expression in relation to the clinicopathological features of breast cancer patients did not reveal any statistically significant associations." (PMID 40299690, 2025). "In contrast, CCR7 has been reported in breast cancer meta-analyses to correlate with worse survival and lymph node metastasis." (PMID 41462979, 2025). "In this model, C-C chemokine receptor type 7 (CCR7) expression was introduced in the EO771 tumor cell line to promote lymph node metastasis, previously also shown to promote lymph node metastasis in other models of breast cancer." (PMID 38148112, 2024). "Finally, we re-examined hotspots of CCR7+ DC and effector CD8+ T cell co-localisation in spatial transcriptomics of CRC, breast cancer and melanoma." (PMID 38267413, 2024). "In future clinical applications, anti-CCR7 antibodies may represent an adjunct therapy to enhance the efficacy of existing chemotherapy techniques, similar to anti-HER2 therapy in breast cancer." (PMID 36980764, 2023). "This is in line with studies showing the involvement of CCR7 and CXCR4 in breast cancer metastasis." (PMID 38055067, 2023). "Yet, recent reports indicate that the role of CCR7 seems to vary between different subtypes of breast cancer, and that expression of CCR7 in breast cancer tissues is not predictive for lymph metastasis." (PMID 38055067, 2023). "Like some of the other studies reviewed in breast cancer, it is unfortunate that the authors did not validate the CCR7 Western blots used in this study with negative controls that lacked CCR7 expression." (PMID 35203305, 2022). "It is also reported that CCR7 has no notable effects on OS in other tumor types such as gastric cancer and breast cancer and SCCHN." (PMID 35874608, 2022). "While some studies report that CCR7 was a useful biomarker to predict lymph node metastasis of breast cancer, others do not." (PMID 35203305, 2022). "This must necessarily lead to an organotropism; e.g., breast cancer cells express high levels of CXCR4 and CCR7, which are responsible for the metastasis formation in LN, lung, liver, and KM, as these organs are rich in corresponding ligands CXCL12 and CCL21 [Chambers3471]." (PMID 35326690, 2022). "We have previously demonstrated that it is the functional activation of both CXCR4 and CCR7, as opposed to their expression levels, that correlates with the invasive and metastatic phenotype of breast cancer cells." (PMID 34685420, 2021). "Interestingly, expression of some immune cell genes and DVL-1 uniquely correlated with luminal breast cancer, such as CD19, CD79A, CD8B, CCR7, CD1C, and STAT5B." (PMID 34659647, 2021). "It has been found that CCR7 is highly expressed in triple negative breast cancer cell lines and breast cancer tissues, and when CCR7 is absent, it can significantly reduce the proliferation, migration, and invasion of triple negative breast cancer cells." (PMID 32253815, 2020).
breast cancer (continued). "Breast cancer e.g., was found to express the chemokine receptors CXCR4 and CCR7 at high levels." (PMID 32547940, 2020). "Moreover, CCL21/CCR7 signalings VEGF-C expression and secretion and promotes breast cancer-induced lymphangiogenesis via LEC activation." (PMID 29599774, 2018). "We did not observe significant changes in CCR7 expression in breast cancer tissue compared to peripheral blood." (PMID 29587679, 2018). "This study used a combination of molecular and cellular assays on primary mammary tumor cells from the MMTV-PyMT transgenic mouse with or without CCR7 to examine the signaling crosstalk between CCR7 and Notch pathways." (PMID 28137279, 2017). "Here, we supposed that CCR7 might induce the invasion, migration, and epithelial–mesenchymal transition (EMT) process of breast cancer." (PMID 28378417, 2017). "The tumor suppressor let-7a is, for example, known to be directly downregulated by EWSR1–ETS, but this decrease in let-7a does not lead to increased CCR7 expression like in breast cancer cells." (PMID 27369431, 2016). "Our in vivo findings indicate that CCR7 is expressed by LECs and therefore promotes LECs recruitment and lymphangiogenesis through the regulation of the expression/secretion of VEGF-C by human breast cancer cells." (PMID 25744065, 2015). "Importantly, short-term lenalidomide exposure further increased the proportion of CD45RO+CCR7+ central memory CD3+CD8+ T cell subset within the XBP1-CTL, leading to enhanced anti-tumor activities against breast cancer, colon cancer and pancreatic cancer cells." (PMID 27668268, 2015). "Prior to the investigation of the role of CCL21/CCR7 pair in VEGF-C production, we have screened the constitutive expression of CCR7, CCL21, and VEGF-C in two well differentiated, luminal type (T47D, MCF-7) and two poorly differentiated basal type (Hs578t, MDA-MB-231) breast cancer cell lines." (PMID 25744065, 2015). "While prior studies have established that COX-2 secretion by breast cancer cells can upregulate CCR7 expression via activation of EP2/EP4 receptors to enhance their invasive capacity, a possible link between CCR7 signaling and VEGF-C expression/secretion has remained untested so far." (PMID 25744065, 2015). "Furthermore, these results corroborate well with our in situ findings outlining a strong correlation between CCR7 and VEGF-C expression in human breast cancer tissues." (PMID 25744065, 2015). "Since our in vitro and in vivo studies have established the roles of CCR7/CCL21 and VEGFR3/VEGF-C axes in breast cancer induced lymphangiogenesis, we have postulated that CCR7 and VEGF-C expressions will be noticeably different in tumor tissues when compared to their non-tumor counterparts." (PMID 25744065, 2015). "Previous studies have found that high expression level of CCR7 in lung cancer, esophageal carcinoma, hepatocellular cancer, breast cancer and melanoma closely related to tumor invasion and lymph node metastasis." (PMID 24040244, 2013). "PyVmT mammary tumor cells expressing CCR7 preferentially colonized the lymph nodes, whereas CCR7 negative PyVmT breast cancer cells metastasized to lung tissue." (PMID 23667660, 2013). "In contrast, CCR7 expression was higher in malignant tissues compared with normal counterpart tissues in 10 of 15 breast cancer patients." (PMID 22251626, 2012). "The results from the present study suggest that targeting of CCL21-CCR7 signaling is a valid approach for breast cancer therapy and that let-7a directly binds to the 3'UTR of CCR7 and blocks its protein expression, thereby suppressing migration and invasion of human breast cancer cells." (PMID 22251626, 2012). "In the present study, we assessed the expression of CCR6, CCR7 and their ligands CCL19, CCL20 and CCL21 using immunohistochemistry in a series of tumors prospectively collected from patients with loco-regional breast cancer treated at the Centre Léon Bérard in 1996 and 1997." (PMID 21624121, 2011).
breast cancer (continued). "The objective of the present study was to investigate the presence of CCR6 and CCR7 chemokine receptors and their ligands in non-metastatic primary breast carcinomas." (PMID 21624121, 2011). "Multicolor immunophenotyping was used to determine the expression of PD‐1, TIM‐3, LAG3, CTLA‐4, CCR7, CD45RO, CD127, CD25, CXCR5, and ICOS molecules on CD3+CD4−CD56−CD8+ cytotoxic T cells freshly obtained from the lymph nodes and the peripheral blood samples of the breast cancer patients." (PMID 38069525, 2023). "Furthermore, the overexpression of CCR7 indicated poor OS in patients having breast cancer, but this prediction was not significant." (PMID 35874608, 2022). "Using the mouse MMTV-PyVMT model (CCR7 negative) that had been selected for metastasis to the lungs, it was confirmed that after implantation of these mammary cancer cells into the mammary fat pad, all mice tested showed lung metastasis with no spread to the lymph nodes." (PMID 35203305, 2022). "In the future, it would be interesting to examine the levels of CCR7 in the actual tumor cells of breast cancer patients in the absence of infiltrating immune cells to better confirm that ET-1 combined with CCR7 promotes migration of tumor cells to the lymph nodes." (PMID 35203305, 2022). "High expression of CCR7 and the EMT markers, Slug and N-cadherin was reported for 60, 65 and 77% of tumors from primary breast cancer tissues obtained from sixty patients after radical mastectomy, which correlated with lymph node metastasis and breast cancer stage." (PMID 35203305, 2022). "Notably, CCR7-reduced anoikis occurred in highly aggressive breast cancer cells, but not in untransformed or non-metastatic cells." (PMID 35203305, 2022). "Although the CCR7 physiological function is known in normal breast epithelial cells, their exact role remains unknown but valuable to be determined in non-metastatic breast cancer cells." (PMID 32340161, 2020). "Thus, we focused on the correlation between CCR7 and AP1 complex in breast cancer." (PMID 30781353, 2019). "Moreover, CCL21/CCR7 chemokine axis has the ability to promote lymphatic endothelial cells proliferation, migration, as well as tube formation in vitro, and this axis also regulates the expression of lymphangiogenic factor VEGF-C by breast cancer cells." (PMID 25744065, 2015). "Chemokine (C-C motif) ligand 19 (CCL19), the cognate ligand for CCR7, induced the activation of extracellular signal-regulated kinase (ERK) and AKT signaling and increased the expression of cell cycle regulatory proteins and proliferation of breast cancer cells." (PMID 24915301, 2014). "Approximately 30% of control breast cancer cells were able to migrate out from the embryo abdomen, but none of the synthetic let-7a or CCR7 siRNA-transfected cells could do so." (PMID 22251626, 2012). "This study investigated a series of matched primary and lymph node metastasis breast cancer tumors to demonstrate whether the expression of the CXCR4 and CCR7 chemokine receptors, along with expression of EGFR, predicts increased risk of metastasis and mortality." (PMID 20181250, 2010). "While CXCR4 and another chemokine receptor, CCR7, are highly expressed on the surface of human breast cancer cells, CXCL12 and a CCR7 ligand, CCL21, are highly expressed in lymph nodes, bone marrow, lung and liver, which form the common metastatic destinations of breast cancer." (PMID 19787093, 2008). "However, anti-CCR7 therapy is not necessarily advantageous; for example, a study adapted a virus middle T-antigen (PyV MT) syngeneic adenocarcinoma mouse model to examine the effects of CCR7 expression on mammary tumor cell metastasis." (PMID 35203305, 2022). "Similarly, in a separate study, although only 11% of skin metastases expressed CCR7 in primary breast cancer patients, in a 13 year follow-up of study, none of the CCR7-negative primary breast cancer patients had skin metastases, which was statistically significant." (PMID 35203305, 2022).